FAM90A15 (family with sequence similarity 90 member A15)
Synonyms: FAM90A15P
Tractability: No criterion of Open Targets' tractability assessment is met for any kind of drug.
Gene: Protein-coding gene on chromosome 8 (7,256,904 to 7,259,914, forward strand). Ensembl gene ENSG00000230045.
Subcellular location (Human Protein Atlas): Nucleoplasm; Nucleoli
Homologues: Orthologues: mouse Fam90a1b (28% identical), mouse Fam90a1a (27% identical), rat Fam90a1l1 (26% identical). Paralogues in human: FAM90A13 (99% identical), FAM90A14 (99% identical), FAM90A5 (99% identical), FAM90A23 (99% identical), FAM90A24 (99% identical), FAM90A3 (98% identical), FAM90A11 (98% identical), FAM90A16 (98% identical), FAM90A17 (98% identical), FAM90A9 (98% identical), FAM90A12 (98% identical), FAM90A18 (98% identical), and 9 more.